RN7SL440P (RNA, 7SL, cytoplasmic 440, pseudogene)
Gene: Miscellaneous RNA gene on chromosome 1 (94,150,738 to 94,151,080, forward strand). Ensembl gene ENSG00000264963.
Homologues: Orthologues: macaque Metazoa_SRP (79% identical), macaque Metazoa_SRP (76% identical). Paralogues in human: RN7SL524P (75% identical), Metazoa_SRP (75% identical), RN7SL718P (73% identical), Metazoa_SRP (72% identical), RN7SL602P (71% identical), Metazoa_SRP (71% identical), Metazoa_SRP (70% identical), Metazoa_SRP (68% identical), Metazoa_SRP (67% identical), RN7SL134P (66% identical), Metazoa_SRP (66% identical), RN7SL624P (66% identical), and 711 more.